SYNE3 (spectrin repeat containing nuclear envelope family member 3)
Description:
As a component of the LINC (LInker of Nucleoskeleton and Cytoskeleton) complex involved in the connection between the nuclear lamina and the cytoskeleton. The nucleocytoplasmic interactions established by the LINC complex play an important role in the transmission of mechanical forces across the nuclear envelope and in nuclear movement and positioning. Probable anchoring protein which tethers the nucleus to the cytoskeleton by binding PLEC which can associate with the intermediate filament system. Plays a role in the regulation of aortic epithelial cell morphology, and is required for flow-induced centrosome polarization and directional migration in aortic endothelial cells.
Synonyms: KASH3; C14orf139; C14orf49; LINC00341; FLJ25605; NET53; Nesprin-3; Nesp3; NCRNA00341
Tractability: Antibody: UniProt predicts a signal peptide or a membrane-spanning region. PROTAC: ubiquitination databases record sites on it; its protein half-life has been measured.
Gene: Protein-coding gene on chromosome 14 (95,407,266 to 95,516,678, reverse strand). Ensembl gene ENSG00000176438.
Subcellular location: Nucleus outer membrane; Nucleus envelope; Rough endoplasmic reticulum
Subcellular location (Human Protein Atlas): Nuclear membrane
Gene Ontology:
Molecular function: actin filament binding; cytoskeleton-nuclear membrane anchor activity; protein binding
Biological process: cytoskeleton organization; establishment of protein localization to membrane; regulation of cell shape; nuclear migration
Cellular component: meiotic nuclear membrane microtubule tethering complex; membrane; nuclear envelope; nuclear membrane; cytoplasm; nuclear outer membrane; rough endoplasmic reticulum
Genetic constraint (gnomAD): Loss-of-function variants: 98 observed, 102.5 expected, observed/expected ratio (o/e) 0.96, 90% interval 0.81 to 1.13. The upper end of that interval is the gene's LOEUF score, 1.13, which puts it in group 4 of 6, group 1 being the genes least tolerant of losing a copy. Missense variants: 1,123 observed, 1,200.5 expected, observed/expected ratio (o/e) 0.94, 90% interval 0.89 to 0.98. Synonymous variants: 524 observed, 516.28 expected, observed/expected ratio (o/e) 1.01, 90% interval 0.94 to 1.09.
Homologues: Orthologues: chimpanzee SYNE3 (98% identical), macaque SYNE3 (87% identical), pig SYNE3 (80% identical), rat Syne3 (78% identical), mouse Syne3 (78% identical), rabbit SYNE3 (75% identical), dog SYNE3 (75% identical), guinea pig SYNE3 (58% identical), tropical clawed frog syne3 (47% identical), zebrafish syne3 (40% identical). Paralogues in human: SYNE1 (20% identical), SYNE2 (19% identical), MACF1 (18% identical), DST (18% identical), SPTBN2 (17% identical), SPTBN1 (16% identical), SPTB (16% identical), SPTBN4 (16% identical), PLEC (15% identical), SPTBN5 (15% identical), DMD (14% identical), UTRN (14% identical), and 24 more.
Diseases named in the same sentence as SYNE3 in open-access papers:
SYNE3 is named in the same sentence as 23 diseases in open-access papers, as found by Europe PMC text mining. Sharing a sentence is not in itself a finding about the gene and the disease. The quoted sentences say what the papers report.
lung carcinoma (3 papers, 2017 to 2020). "As previous studied have revealed SYNE3 connection with lung cancer development compared with few reports on BRCA, so we chose to focus more on SYNE3 role in lung cancer in this article." (PMID 32948197, 2020).
acute myeloid leukemia (1 paper, 2020). Acute myeloid leukemia (AML) is a group of neoplasms arising from precursor cells committed to the myeloid cell-line differentiation. "However, only in acute myeloid leukemia (LAML), SYNE3 expression level is higher in tumor tissue compared with normal one (P < 0.0001)." (PMID 32948197, 2020).
invasive breast carcinoma (1 paper, 2020). A carcinoma that infiltrates the breast parenchyma. "Meanwhile, according to GEPIA database, SYNE3 was significantly expressed less in 9 cancer types, including invasive breast carcinoma (BRCA), lung adenocarcinoma (LUAD), and lung squamous cell carcinoma (LUSC)(P < 0.0001), which were consistent with our IHC results in these tumors." (PMID 32948197, 2020).
lung adenocarcinoma (1 paper, 2020). A carcinoma that arises from the lung and is characterized by the presence of malignant glandular epithelial cells. "Additionally, we constructed a RP11-2B6.2-miR-149-5p-/RP11-67L2.2-miR-330-3p-SYNE3 ceRNA network and a SATB1-miR-149-5p-SYNE3 transcriptional network in lung adenocarcinoma to support the tumor-suppressing role of SYNE3." (PMID 32948197, 2020). "In addition to tumor metastasis, the role of SYNE3 in apoptosis, maintenance of nuclear stability, and tumor microenvironment regulation in cancer are more prominent, especially in lung adenocarcinoma." (PMID 32948197, 2020).
medulloblastoma (1 paper, 2020). A malignant, invasive embryonal neoplasm arising from the cerebellum. "Interestingly, the fraction of M2 macrophages in Group 4 medulloblastoma were positively correlated with the risk score and were significantly correlated with the expression level of four signature genes (CCNY, SYNE3, CYB5D2, and SELENOV) and four hub genes (GLI2, PAX6, RUNX2, and ZIC1)." (PMID 32508873, 2020).
cancer (7 papers, 2017 to 2022). A tumor composed of atypical neoplastic, often pleomorphic cells that invade other tissues. "Our study revealed the unexpected anti-cancer functions of SYNE3, and provided a new perspective of SYNE family in tumors, though still lacking experimental verification." (PMID 32948197, 2020). "Next, we predicted miRNA targeting SYNE3 and built a competing endogenous RNA (ceRNA) network and a transcriptional network by analyzing data from the cancer genome atlas (TCGA) database." (PMID 32948197, 2020). "For its potential roles in cancer, the prognostic value of SYNE3 was discussed in patients with tumors." (PMID 32948197, 2020). "In a tumor, invasiveness and metastasis rely on the integrity of the LINC complex, while the role of SYNE3/nesprin-3 in cancer is rarely studied." (PMID 32948197, 2020). "In most cases, the expression of SYNE3 was also downregulated in tumor, indicating its anti-cancer roles in these cancer types, especially in LUAD and CESC." (PMID 32948197, 2020). "Based on these, SYNE3 may suppress cancer by promoting tumor apoptosis, which can be realized through adjustment of the cell cycle, recruitment of immune cells, and alteration of nucleoskeleton and ribosome." (PMID 32948197, 2020). "While in the corresponding tumor samples, SYNE3 staining was only weakly present in cancer cells." (PMID 32948197, 2020). "First, we screened cancer types whose immune infiltration was correlated with SYNE3 expression." (PMID 32948197, 2020). "In liver, only the cancer cells presented weak SYNE3 staining in the cytoplasm." (PMID 32948197, 2020). "Our study explored novel anti-tumor functions and mechanisms of SYNE3, which might be useful for future cancer therapy." (PMID 32948197, 2020). "Therefore, in our study, we hoped to provide some basic knowledge of SYNE3 and analyze its roles in cancer." (PMID 32948197, 2020). "On the contrary, negative LASSO coefficients were found for the genes ADRB2, CRYAB, NR4A1, CMTM5, ZBTB16, SYNE3, and RAD51, which were downregulated in cancer compared with normal samples." (PMID 36552262, 2022). "Accordingly, we found that SYNE3 expression was significantly correlated with dendritic cell, neutrophil, CD4 + T cell, macrophage, CD8 + T cell and B cell in 30, 30, 27, 26, 25, 25 and 22 types of cancer respectively." (PMID 32948197, 2020).
tumor (5 papers, 2017 to 2021). "Higher SYNE3 expression was linked to better clinical outcomes in our analysis, suggesting its tumor-suppressing functions." (PMID 32948197, 2020). "At last, we investigated how SYNE3 expression affected tumor immune infiltration, thus influencing prognosis." (PMID 32948197, 2020). "Though previous researches revealed its role in mediating tumor metastasis, we found higher SYNE3 expression correlated with even better clinical outcomes." (PMID 32948197, 2020). "As BALB/c mice was a widely-used animal model in studies on tumorigenesis and tumor migration, we first detected the SYNE3 expression of various normal tissues in BALB/c mice." (PMID 32948197, 2020). "SYNE3 expressed significantly lower in tumor tissues of LUAD, and both two miRNAs expressed higher in tumor tissues instead." (PMID 32948197, 2020). "Overall, our study firstly provided an overview of SYNE3 expression in diverse normal and tumor tissues." (PMID 32948197, 2020). "SYNE3 expression level had prognostic value in tumors, possibly by stabilizing nucleus, promoting tumor cells apoptosis, and altering tumor microenvironment." (PMID 32948197, 2020). "In our study, SYNE3 presented lower expression in both mRNA and protein level in tumor tissues compared with that in normal tissues." (PMID 32948197, 2020). "Based on our results in IHC and bioinformatic analysis, BRCA, LUSC and LUAD presented most significant differences in both mRNA and protein level of SYNE3 between normal and tumor tissues." (PMID 32948197, 2020). "SYNE3 showed a good correlation with tumor immune infiltration, especially in LUAD, as its OS was most relevant with its tumor microenvironment, especially with B cell and DC cell." (PMID 32948197, 2020). "As a linker protein of cytoskeleton and nucleoskeleton, SYNE3/nesprin-3 has been shown to play a vital role in 3D cell migration and tumor cell movement in previous studies." (PMID 32948197, 2020). "SYNE3 expression, miRNAs expression and expression of lncRNAs were compared between tumor tissues of LUAD and normal ones." (PMID 32948197, 2020). "We then analyzed tumor-suppressing functions of SYNE3, showing that SYNE3 might engage in apoptosis mediation of tumor cells." (PMID 32948197, 2020). "Therefore, we supposed that higher expression of SYNE3 helped with the production and collection of B cell and DC cell so that SYNE3 altered tumor microenvironment and presented significant and reasonable prognostic value in LUAD." (PMID 32948197, 2020). "However, with present researches, our knowledge of nesprin-3/SYNE3 in tumor is still relatively limited." (PMID 32948197, 2020). "Moreover, SYNE3 expression can impact immune cell infiltration as well, adjusting the local anti-tumor immunity to be more active and effective." (PMID 32948197, 2020). "However, these researches too limited to reveal SYNE3 functions in the tumor." (PMID 32948197, 2020). "Therefore, SYNE3 participated in some anti-tumor events, and there might be various mechanisms to adjust SYNE3 expression." (PMID 32948197, 2020). "Firstly, expression profile and histological distribution of SYNE3 in various BALB/c mice tissues, normal human tissues, and paired tumor tissues were displayed." (PMID 32948197, 2020). "We first detected SYNE3 in BALB/c mice, normal human tissues, and the paired tumor tissues, then used bioinformatics databases to verify our results." (PMID 32948197, 2020).
SYNE3 also shares sentences with these, for which no sentence is quoted: colorectal cancer (3 papers); bladder cancer (2); breast carcinoma (2); cardiomyopathy (1); cervical squamous cell carcinoma (1); endocervical adenocarcinoma (1); hepatocellular carcinoma (1); liver cancer (1); lung squamous cell carcinoma (1); lymph node metastasis (1); ovarian carcinoma (1); pancreatic cancers (1); renal clear cell carcinoma (1); Skin Cutaneous Melanoma (1); squamous cell carcinoma of head and neck (1); uterine corpus endometrial carcinoma (1).